CTLA4 (cytotoxic T-lymphocyte associated protein 4)
Diseases named in the same sentence as CTLA4 in open-access papers (continued):
Sharing a sentence is not in itself a finding about the gene and the disease.
melanoma (continued). "Using a previously optimized regimen, we tested the ability of our combined modality ISV + α-CTLA-4 treatment to eliminate B78 GD2+ melanoma tumors on the flank and establish immune memory." (PMID 32690669, 2020). "As PTEN deletion leads to PI3K activation, treatment of mouse models of melanoma with selective PI3Kβ inhibitors improved the efficacy of Anti-PD-1 and Anti-CTLA-4 antibodies." (PMID 33344447, 2020). "Under these conditions, the response of melanoma cells to anti-PD-1 or anti-CTLA-4-based immunotherapy highly increased." (PMID 32858889, 2020). "Low baseline LDH level, high relative/absolute eosinophil counts, and relative lymphocyte counts are correlated with prolonged OS in melanoma anti-PD-1 and CTLA-4 treatment." (PMID 31968651, 2020). "Some of these drugs approved for advanced stages of melanoma include nivolumab and pembrolizumab (PD-1 inhibitors), ipilimumab (anti-CTLA4 antibody) and the oncolytic virus talimogene laherparepvec (TVEC)." (PMID 31820036, 2020). "Monoclonal antibodies against CTLA-4, PD-1, or PD-L1 have been tested in clinical trials and found effective for some patients with advanced melanoma or non-small cell lung cancer." (PMID 32326073, 2020). "In one of the largest phase III trials of CTLA-4 checkpoint blockade to date, ipilimumab was tested in patients with previously treated malignant melanoma." (PMID 32679922, 2020). "Monoclonal antibodies against cytotoxic T-lymphocyte-associated antigen 4 (CTLA-4), ipilimumab, and programmed cell death protein 1 (PD-1), pembrolizumab and nivolumab, are approved for patients with advanced melanoma." (PMID 32161584, 2020). "Monoclonal antibodies against immune checkpoint receptors, such as CTLA-4, PD-1, and PD-L1, have demonstrated significant results in the treatment of multiple advanced cancers, including melanoma, NSCLC, head and neck, and bladder cancers." (PMID 32260561, 2020). "Combination therapies, such as ipilimumab (CTLA-4 inhibitor) and nivolumab (PD-1 inhibitor), which are commonly used for advanced melanomas, intuitively bear more cost." (PMID 32679922, 2020). "An increased presence of plasmablasts had previously been described in the blood of melanoma, lung, and renal cell carcinomas patients responding to anti-CTLA-4 and anti-PD-1 therapies." (PMID 32457745, 2020). "Many studies have shown that cellular immune function is decreased when TILs in melanoma tissues express high inhibitory receptors, such as PD-1, CTLA4, and TIM-3." (PMID 32964032, 2020). "It has been reported that some transplant recipients treated with ipilimumab to treat malignant melanoma developed graft failure 23-25, highlighting the significance of CTLA-4 in the maintenance of transplant tolerance." (PMID 32724457, 2020). "A phase I study using the combination treatment of CD40 agonist with anti-CTLA-4 antibody, tremelimumab, for melanoma patients resulted in a 27.3% objective response rate and increased T cell activation and infiltration." (PMID 35582437, 2020). "A study investigating the changes in the TME during anti-PD-1 treatment of anti-CTLA-4-resistant melanoma patients reported that, although the density of tumor-infiltrating lymphocytes did not significantly change, their cytolytic activity increased." (PMID 32457745, 2020). "In preclinical models and patients with melanoma, the combination of Anti-CTLA-4 and Anti-PD-1 therapy can impair the anti-tumor immunity under the condition of low tumor load." (PMID 33344447, 2020). "Recently approved immunotherapies with ICI (anti-PD-1, anti-PD-L1 and anti-CTLA-4 antibodies) have revolutionized the treatment of melanoma." (PMID 32235439, 2020). "CTLA-4-targeting antibodies were approved for melanoma treatment in 2011, making them the first approved form of ICB for cancer therapy." (PMID 33170123, 2020).
melanoma (continued). "The most often used intervention in melanoma clinical trials was ipilimumab (immunotherapy checkpoint inhibitor, targeting CTLA-4), described as the applied intervention in 251 trials." (PMID 30884760, 2019). "In 2011, the U.S. Food and Drug Administration (FDA) approved ipilimumab (anti-CTLA-4) for the treatment of advanced melanoma, followed by pembrolizumab and nivolumab (anti-PD-1) in 2014." (PMID 31540045, 2019). "In mice established with sarcoma and melanoma, 2 weeks of broad-spectrum antibiotics and rearing in specific pathogen-free conditions adversely affected survival with PD-1 ± CTLA-4 blockade." (PMID 30887236, 2019). "For melanoma, a 67% response rate was observed for patients with RNA-seq high treated with an anti-CTLA4 agent, which increased to 80% when analyzed for anti-PD-1 therapy alone." (PMID 30678715, 2019). "Using both a TLR9 agonist (MGN1703) and a CTLA-4 antibody (9D9-IgG2a) of increased potency cured 50% of bi-lateral B16-F10 melanoma." (PMID 31771649, 2019). "Intratumoral expression of the NK cell marker CD56 has been shown to correlate with clinical response to ipilimumab in patients with melanoma, suggesting that anti-CTLA-4-induced Treg depletion is mediated at least in part by NK cells." (PMID 30975201, 2019). "Murine studies demonstrated that B16 melanoma cell rejection in mice was improved by combined anti-CTLA-4 and anti-PD-1 antibody therapies." (PMID 30941125, 2019). "The use of an anti-CTLA-4 mAb (tremelimumab or ipilimumab) to treat prostate cancer and melanoma patients results in broadening of the T cell repertoire, in keeping with this mechanism of action." (PMID 30788290, 2019). "Two clinical trials using an anti-CTLA-4 agent (ipilimumab) demonstrated improved overall survival of patients with malignant melanoma." (PMID 31455032, 2019). "Monoclonal antibodies targeting CTLA-4 and PD-1 have now been approved for the treatment of melanoma." (PMID 30941125, 2019). "Anti-CTLA-4 was approved for treatment of melanoma followed by inhibitors of PD-1 or PD-L1, which have been approved to treat, in addition to melanoma, multiple tumor types." (PMID 31200747, 2019). "We previously observed that the addition of anti-CTLA-4 to RT and IT-IC was effective against mice bearing a single large primary or two B78 melanoma tumors." (PMID 31810498, 2019). "CTLA-4 has become a charming target for the treatment of melanoma aiming to strengthen effector T cell function and achieve durable response based on the negatively regulated T cell activation." (PMID 31134073, 2019). "The efficacy of the immunological approach was first proven in advanced melanoma with the anti CTLA-4 mAb Ipilimumab." (PMID 30769874, 2019). "Several studies showed that increased frequencies of memory T cells or decreased frequencies of naïve-phenotype CD4+ or CD8+ T cells in the blood were correlated with better outcomes in anti-CTLA4-treated melanoma patients." (PMID 31275310, 2019). "Following immunization with a GVAX vaccine, rosiglitazone treatment promotes increased B16F10 melanoma tumor rejection, both alone and when combined with anti-CTLA4 immunotherapy." (PMID 31212694, 2019). "The data exploring the association between anti-CTLA-4 antibody-induced IRAEs and ICI efficacy arises largely from patients with melanoma, with mixed results." (PMID 31730012, 2019). "Low SCNA levels correlated with long-term survival after anti-CTLA-4 immunotherapy for melanoma and were better for predicting survival than the number of mutations." (PMID 30232514, 2019). "Here we show that intra-tumoral administration of the TLR9 agonist ODN1826 synergizes with CTLA-4 blockade to promote rejection of bi-laterally implanted B16-Ovalbumin (B16-Ova) melanoma." (PMID 31771649, 2019). "A recent study demonstrated the anti-tumor efficacy of anti-CTLA-4 and anti-PD-1 in the low tumor burden state in pre-clinical melanoma model as well as in melanoma patients." (PMID 31475002, 2019).
melanoma (continued). "In another study employing mass cytometry, the peripheral blood of patients with melanoma was profiled to find predictive biomarkers of response to anti-PD-1 or anti-CTLA-4 therapy." (PMID 31775882, 2019). "Through co-expression of PD-1, CTLA-4, and PD-L1, melanoma cells are able to inhibit antigen presenting cells such as DCs by direct binding of CD80 and CD86 through CTLA-4 and by engagement of PD-L1 through PD-1." (PMID 31192129, 2019). "Recent understanding of the molecular background of melanoma development and progression has resulted in promising novel therapies targeting mutant B-Raf enzyme, or the CTLA-4- or PD-1-immune checkpoints in advanced, unresectable cases." (PMID 31426515, 2019). "Using flow and mass cytometry, combined checkpoint inhibition was studied in patients with advanced melanoma compared with patients receiving either anti-CTLA-4 or anti-PD-1 alone." (PMID 31775882, 2019). "Tumor neo-antigen load and mutational burden have also been correlated with response to anti-CTLA-4 therapy and overall survival with anti-PD-1 treatment in patients with melanoma." (PMID 30747243, 2019). "During a prospective assessment of clinical data from 30 patients with melanoma prior to anti-CTLA-4 treatment (ipilimumab, n = 21) or anti-PD-1 treatment (pembrolizumab, n = 9), baseline CD45RO+CD8+ T-cell levels correlated with ipilimumab response." (PMID 31775882, 2019). "Combined ICI therapy with the anti-PD-1 mAb nivolumab, and anti-CTLA-4 mAb ipilimumab in clinical trials for melanoma led to higher rates of hypophysitis than with nivolumab monotherapy." (PMID 31511065, 2019). "Intratumoural administration of DCs electroporated in vitro with TriMix mRNA and melanoma antigens resulted in durable clinical benefits in patients with advanced melanoma in combination with anti-CTLA-4 mAb." (PMID 31091774, 2019). "This is illustrated by the particular effectiveness of both nivolumab, and pembrolizumab (targeting PD-1) and ipilimumab (targeting CTLA-4) against a subset of patients with Non-Small Cell Lung Cancer (NSCLCs) and melanoma." (PMID 31406485, 2019). "Since the approval of cytotoxic T lymphocyte-associated protein 4 (CTLA-4) and programmed cell death protein 1 (PD-1) inhibitors for the treatment of melanoma, immunotherapy has emerged as a potential alternative treatment option in clinical practice." (PMID 31464625, 2019). "Initial studies with ipilimumab, a CTLA-4 antibody, in melanoma patients with brain metastases showed modest responses, which was largely impacted by use of dexamethasone." (PMID 30886831, 2019). "Immune checkpoint inhibitors including anti-CTLA-4 and anti-PD-1/PD-L1 antibodies are yielding impressive responses in melanoma and NSCLC BM." (PMID 31803366, 2019). "Despite a significant heterogeneity was observed, higher levels of CTLA-4 and PD-L2 expression were found in melanoma patients, who benefit from CTLA-4 antibodies." (PMID 31555274, 2019). "In humans, the anti-CTLA-4 antibody (Ipilimumab) has already been manufactured and used on patients with melanoma." (PMID 31665022, 2019). "Of note, in patients with melanoma treated with anti-CTLA-4, the melanoma-reactive CD8+ T cell response in peripheral blood was found to be significantly increased." (PMID 31379886, 2019). "We have further demonstrated that small molecule inhibitors of the PORCN acyltransferase enzyme, which effectively block Wnt ligand release, synergistically enhances the efficacy of anti-CTLA-4 antibody immunotherapy in pre-clinical models of melanoma." (PMID 31921140, 2019). "Since this phenotype is common in tumors that present with WNT activation, inhibitors of canonical WNT signaling can be combined with CTLA4-blocking mAbs to suppress the progression of melanoma in mice." (PMID 31616443, 2019). "To conclude, the novelty of our study is the combination of gp100 or OVA DNA vaccine with dual CTLA-4/PD-1 immune checkpoint blockade in a murine melanoma model." (PMID 31150505, 2019).
melanoma (continued). "Patients received anti-PD-1 or anti-CTLA-4 therapy for either metastatic or unresectable melanoma, renal cell carcinoma (RCC), or non-small cell lung cancer (NSCLC)." (PMID 31450659, 2019). "In contrast to our finding, anti-CTLA-4 has been previously proposed to be safer than and preferable to anti-PD-1 as the first-line therapy for melanoma in SOT recipients." (PMID 30992053, 2019). "Here we compare three different patient groups with disturbances in the CTLA-4 pathway—CTLA-4-haploinsufficiency, LRBA-deficiency, and ipilimumab-treated melanoma patients." (PMID 31156616, 2019). "Both PD-1/PD-L1 or CTLA-4 checkpoint inhibitors have shown activity in patients with melanoma brain metastases, with a response rate of up to one third of patients." (PMID 30975225, 2019). "In 2002, the first clinical trial dedicated to “emerging class of immunomodulatory antibodies” (monoclonal antibodies to induce CTLA-4 blockade) in melanoma patients was published." (PMID 30884760, 2019). "Blockade of CTLA-4 in a series of preclinical and clinical trials has been demonstrated to generate an antitumor immunological effect, particularly in patients with malignant melanoma." (PMID 31455032, 2019). "Some of the more encouraging data is the long-lived tumor regression arising from CTLA-4-inhibiting mAbs in patients with advanced melanoma." (PMID 30975211, 2019). "To validate further these observations, we analyzed the inflammasome gene expression profile in longitudinal tumor biopsies from melanoma patients treated sequentially with anti-CTLA-4 and anti-PD-1 mAb." (PMID 31085177, 2019). "In vivo tests with tumor bearing mice (melanomas) model showed that CTLA-4 Ab loaded silica foam significantly enhanced antitumor activity compared to free antibodies, attributed to the prolonged release and protection of antibodies at tumor sites." (PMID 31119124, 2019). "CTLA-4 is also expressed on human tumor cell lines including breast carcinoma, osteosarcoma, colon carcinoma and melanoma." (PMID 31192129, 2019). "Melanoma and lung cancer are two tumors currently treated with immune checkpoint inhibitors directed to PD-1/PD-L1 or CTLA-4." (PMID 31500143, 2019). "Recently, predictors of irAEs have been performed mainly on patients with melanoma treated with anti-CTLA-4 antibody ipilimumab." (PMID 31575933, 2019). "Nearly 15 years later, a seminal clinical study demonstrated that antibody-mediated inhibition of CTLA-4 led to a significant improvement in overall survival in patients with advanced melanoma." (PMID 31439034, 2019). "Patients with advanced melanoma treated the CTLA-4-blocking antibody tremelimumab, were analysed for changes in glycolysis using, [18F]FDG and DNA-synthesis using [18F]FLT." (PMID 31656546, 2019). "Anti-CTLA-4 and anti-PD-1 combination was also tested for the treatment of melanoma in adjuvant and neoadjuvant settings." (PMID 31196207, 2019). "Concomitant treatment with antibody to cytotoxic T lymphocyte-associated antigen-4 (anti-CTLA4) and anti-PD1 was previously reported to generate a rapid and strong tumor regression in melanoma patients." (PMID 30796212, 2019). "In mouse tumor models (melanoma and colorectal cancer), several groups have clearly shown that surrogate anti-CTLA-4 antibody-mediated anti-tumor efficacy is dependent on Fc effector functions and correlate with depletion of tumor-infiltrating Tregs." (PMID 30863404, 2019). "The anti-cytotoxic T-lymphocyte- associated protein 4 (CTLA-4) monoclonal antibody (mAb) ipilimumab is associated with hypophysitis in a dose-dependent manner, with rates up to 21% in patients with melanoma treated with a dose of 9 mg/kg." (PMID 31511065, 2019). "The CTLA-4 blocking antibody ipilimumab has demonstrated substantial and durable effects in patients with melanoma." (PMID 30975201, 2019).
melanoma (continued). "A male gender driven obesity paradox (improved survival for overweight/obese patients compared to normal weight) was recently shown in melanoma in the context of checkpoint inhibition (anti-PD-1/anti-CTLA4 monotherapy) in a pooled meta-analysis." (PMID 30922394, 2019). "Phase III trials have confirmed these findings showing improved outcomes for advanced-stage melanoma patients when treated with both anti-CTLA-4 and anti-PD-1 therapeutics, which showed benefits for patients with PD-L1 negative tumors." (PMID 30941125, 2019). "Anti-CTLA4 antibody (Ipilimumab) was first approved by FDA in 2011 for the treatment of melanoma, following the result from the phase III trial, showing significant overall survival benefit compared to gp100 vaccine alone." (PMID 31816940, 2019). "In the last 10 years, MAP kinase pathway–targeted therapies (BRAF and MEK inhibitors) and immune checkpoint inhibitors blocking CTLA-4 and PD-1 have revolutionized the management of advanced melanoma and significantly prolonged patient survival." (PMID 31028434, 2019). "Immune-related adverse events are commonly observed following CTLA-4 inhibition in melanoma treatment, and a spectrum of these conditions are also observed in individuals with germline haploinsufficiency of CTLA4." (PMID 31396201, 2019). "Immune-related pulmonary toxicity was most frequently observed in trials of lung cancer and of melanoma patients treated with the combination of the anti-cytotoxic T lymphocyte antigen (CTLA)-4 and the anti-programmed cell death-1 (PD-1) antibodies." (PMID 30841554, 2019). "Most clinical data about toxicity from combined modality regimes are derived from retrospective CTLA-4-targeting melanoma series and comprise autoimmune phenomena (e.g. hypophysitis) and – in case of cerebral radiotherapy – brain necroses." (PMID 31703637, 2019). "Combination therapy utilizing both a CTLA-4 inhibitor and PD-1 inhibitor have been applied towards advanced melanoma treatment and is also being explored in other cancers at the expense of higher risk for irAE." (PMID 30777137, 2019). "We compared the CTLA-4 protein expression in Tregs (CD4+ Foxp3+) from these patients to five ipilimumab-treated melanoma patients, since they also have disruption of the CTLA-4 pathway and can experience a wide array of autoimmune complications." (PMID 31156616, 2019). "CTLA4 mRNA levels from melanoma patients under therapeutic CTLA-4 blockade (ipilimumab) were increased compared to patients with either CTLA4 or LRBA mutations that were clinically stable with abatacept treatment." (PMID 31156616, 2019). "Patients received anti-PD-1, anti-CTLA-4 or interferon alpha-2b therapy for either metastatic or unresectable melanoma, renal cell carcinoma (RCC), non-small cell lung cancer (NSCLC), or neuroendocrine tumors (NET)." (PMID 31450659, 2019). "Durable clinical responses and prolonged survival rate have been shown in patients with melanoma and highly immunogenic cancers using monoclonal antibodies (mAb) targeting CTLA-4 or PD-1." (PMID 30987642, 2019). "In studies of patients with melanoma, the incidence of these side effects was higher when using the combination of the anti-PD-1 nivolumab plus the anti-CTLA-4 ipilimumab (from 2% and 3% in monotherapy respectively to 9% in combo trials)." (PMID 30841554, 2019). "Ipilimumab, an anti-CTLA-4, was approved by the FDA for the treatment of metastatic and high-risk resected melanoma in 2011, and tremelimumab is currently under investigation as another potential anti-CTLA-4." (PMID 30506221, 2019). "Expression of CTLA-4, PD-1, and PD-L1 immune checkpoint proteins was upregulated in H-1PV-infected melanoma cells." (PMID 31192129, 2019). "In 2011, the FDA approved the first anti-CTLA-4 antibody, ipilimumab (IgG1 wild-type), for the treatment of melanoma." (PMID 30863404, 2019).